CTLA4 (cytotoxic T-lymphocyte associated protein 4)
Diseases named in the same sentence as CTLA4 in open-access papers (continued):
Sharing a sentence is not in itself a finding about the gene and the disease.
melanoma (continued). "Anti-CTLA4 monoclonal antibodies are used in several clinical settings, including stage III/IV melanoma, renal cell carcinoma, non-small-cell lung carcinoma (NSCLC) and prostate cancer." (PMID 34899700, 2021). "There is an additional report of 10 patients with melanoma who developed ICI hepatotoxicity from PD-1 and/or CTLA-4 inhibition." (PMID 33494227, 2021). "We used the transcriptomic and clinical data from melanoma and glioblastoma patients of anti-PD1 or anti-CTLA4 therapy to predict the immunotherapy response of cohorts with different STAT3/CDK2/4/6 expression." (PMID 33668805, 2021). "CTLA4-specific or PD1-specific antibodies have produced significant and long-lasting clinical responses in patients with advanced melanoma." (PMID 33506034, 2021). "Anti-PD-L1 mAbs have been developed along with anti-CTLA-4 and anti-PD-1 antibodies for immune checkpoint inhibitor (ICI) therapy, and anti-PD-1 mAbs are now used as first line treatment in melanoma." (PMID 33809167, 2021). "Ipilimumab (MDX-010, Yervoy; Bristol-Myers Squibb), a fully human mAb against CTLA-4, was approved by FDA for thetreatment of metastatic melanoma and in patients with melanoma and preexisting auto immune disorders." (PMID 35011682, 2021). "Therapy with immune checkpoint blockers such as ipilimumab (anti-CTLA4), and nivolumab and pembrolizumab (anti-PD1), has been established as the standard-of-care for melanoma with a significant improvement in OS." (PMID 33520112, 2021). "More recently, melanoma patients were treated with ATRA and anti-CTLA4 and this was shown to reduce circulating MDSCs and expression of immunosuppressive genes." (PMID 34885021, 2021). "Checkpoint inhibitors targeting CTLA-4, PD-1, and PD-L1 have yielded response in NSCLC and melanoma." (PMID 34093667, 2021). "Currently, significant strides have been made in T cell-based immunotherapy for cancer treatment since ipilimumab, an anti-cytotoxic T lymphocyte antigen-4 (CTLA-4) antibody, was approved by FDA for use in melanoma treatment." (PMID 34336860, 2021). "Following up on this finding and to dissect melanoma or immune cells as source of CTLA-4 expression, we performed IHC for CTLA-4 protein expression in our melanoma cohort prior ipilimumab treatment." (PMID 33196890, 2021). "Recently, B7 family members have attracted more attention, especially following the successful treatment in advanced melanoma, lung cancer, and other solid tumors with anti-PD1/PDL1 and anti-CTLA4 therapies." (PMID 34079802, 2021). "Total study populations for ICIs (melanoma, NSCLC, HCC, and RCC) and type of ICI interventions (anti-PD-1 [n = 5], anti-CTLA-4 [n = 2], and a combination of anti-PD-1 and anti-CTLA-4 [n = 3]) varied across studies." (PMID 34638308, 2021). "Recently, using a murine model of melanoma, intradermal IL-12 GET plus DNA vaccination combined with anti-CTLA4/PD-1 blockade led to tumor reduction through long-lasting antigen-specific IgG antibodies together with antigen-specific CD8+ T cells." (PMID 34358144, 2021). "Co-staining with pan anti-CTLA-4 (AF488) and anti-sCTLA-4 (AF555) revealed and differentiated the presence of both CTLA-4 receptor and sCTLA-4 in melanoma cell lines." (PMID 35069536, 2021). "Combined inhibition of CTLA4 and PD1 has high activity against brain metastasis and the highest 5-year overall survival rate of all therapies used in advanced melanomas, although immune-related adverse events occur frequently." (PMID 34638331, 2021). "BTLA has structural and functional similarities with CTLA-4 and PD-1, and it has been found to be highly expressed in tumor antigen-specific CD8+ T cells of melanoma patients after peptide vaccinations." (PMID 34371708, 2021). "An important consideration is that the CNMR collected data from December 2011 and the most important drug in the field of melanoma, like BRAF inhibitors, anti-CTLA4, anti-PD-1 were approved in the following years." (PMID 34307142, 2021).
melanoma (continued). "Anti-CTLA-4-TGF-βRII fused antibodies significantly reduce the numbers of Tregs and increase CD8+ T cells in a melanoma mouse model." (PMID 34806028, 2021). "Immune checkpoint blockade (ICB) with therapeutics such as the anti-CTLA-4 antibody ipilimumab (IPI) and anti-PD-1 antibodies nivolumab (NIVO) and pembrolizumab have revolutionized the treatment of advanced melanoma, producing durable clinical benefit." (PMID 34641962, 2021). "CTLA-4 is highly expressed on activated Tregs and also upregulated in activated CD4+ and CD8+ T cells in melanoma tissues compared to other tumors." (PMID 34806028, 2021). "Since immunotherapeutic regimens only benefit from a subset of patients, in the melanoma murine model it was investigated the efficacy of the ALDH CSC-DC vaccine combined with a dual blockade of PD-1 and CTLA-4." (PMID 34572009, 2021). "At present, drugs for melanoma include small molecule inhibitors for BRAF or MEK, anti-CTLA4 antibody, anti-PD1 antibody, and modified oncolytic herpes virus talimogene laherparepvec (T-VEC)." (PMID 34900983, 2021). "In B16 melanoma models, NK cells and CD8+ T cells synergistically clear tumors in response to anti-CTLA-4 and IL-2 treatment." (PMID 34376232, 2021). "In the RET melanoma model, diet-based host conditioning increased the efficacy of combination ICB (cICB; anti–PD-1 plus anti–CTLA-4), with significant differences observed as early as after the first systemic injection of cICB." (PMID 33320838, 2021). "Recent studies have demonstrated that melanoma can be efficiently overcome by treating with antibodies against PD1, PD-L1/2 and CTLA-4." (PMID 34805153, 2021). "Ipilimumab (anti-CTLA4), pembrolizumab and nivolumab (PD1 inhibitors) are the available ICIs used in melanoma for ipilimumab since 2014, for pembrolizumab and nivolumab since 2015." (PMID 33634154, 2021). "In several tumor contexts, including melanoma, it is known that the interaction between PD1 and CTLA-4 and their ligands induces programmed death (apoptosis) of T lymphocytes by regulation of several pathways involved in cell survival and proliferation." (PMID 33917181, 2021). "Similar to anti-CTLA4-treated patient cohort, NLRC5 and HLA-B was reduced in non-responders, along with a similar trend for B2M in anti-PD1-treated melanoma patients." (PMID 33547395, 2021). "This is the first study to investigate the effects of neoadjuvant CTLA-4 blockade and IFN-α2b therapy in combination upon gene expression profiles in tumors of patients with locally/regionally advanced melanoma." (PMID 33428680, 2021). "Some studies demonstrated that, in melanoma tumors and TNBC, the WNT signalling can control the expression of PD-L1 and CTLA-4, as well as have the capacity to regulate the tumor-immune cycle in all steps." (PMID 34829916, 2021). "The CPI anti-CTLA-4 has been studied with immunocytokine therapy and an anti-GD2-IL-2 immunocytokine increased the efficacy of CTLA-4 CPI in melanoma models in a T cell-dependent manner." (PMID 33803078, 2021). "Previously, in patients with advanced melanoma, RCC and NSCLC, the inhibition of both the PD-1 and CTLA-4 pathways elevated survival and objective response rates." (PMID 34575943, 2021). "This was further confirmed in preclinical experiments using a B16 melanoma model with IFNGR1 knock-down (IFNGR1KD) that showed impaired IFN-γ signaling and reduced sensitivity to anti-CTLA-4 therapy." (PMID 34830176, 2021). "Collectively called ‘checkpoint inhibitors’ (CPI), the two main classes targeting CTLA4 and the PD1/PD-L1 axis were broadly evaluated for their role in melanoma treatment, being the first disease to receive approval for non resectable metastatic disease." (PMID 32282861, 2020). "Another CTLA4 inhibitor ipilimumab, an FDA-approved drug for treatment of melanoma, induced in combination with cryoablation antitumor activities of immune system in early stage breast cancer patients." (PMID 32947901, 2020).
melanoma (continued). "Latest clinical guidelines on melanoma management consider immune checkpoint blockade (anti-PD-1 alone or in combination with anti-CTLA4) as a first-line treatment option for unresectable stage III and IV melanoma patients." (PMID 32235439, 2020). "Recent studies reported on a significantly longer overall survival in melanoma patients who were treated with the combination of anti‐PD‐1/anti‐CTLA‐4, or with anti‐PD‐1 alone, compared to those treated with anti‐CTLA‐4 alone." (PMID 32249551, 2020). "We assessed the therapeutic efficacy of the MMP2/9 inhibitor SB-3CT in combination with the anti-CTLA-4 antibody in two tumor models, B16F10 melanoma and LLC." (PMID 32988398, 2020). "Thereafter, ipilimumab (targeting CTLA-4, FDA-approved in 2011) and spartalizumab (humanized IgG4-PD-1) were developed to treat melanoma patients." (PMID 32899183, 2020). "Early studies in metastatic melanoma show that treatment with anti-CTLA-4 blocking antibody (ipilimumab) confers significant therapeutic benefit, leading to the first FDA approval of ipilimumab for melanoma patients." (PMID 33322601, 2020). "Another study showed that all melanoma cell lines analyzed expressed CTLA-4, and approximately 67% of melanoma specimens expressed CTLA-4 at different levels of intensity." (PMID 31911758, 2020). "Anti-CTLA-4 Nbs have been generated and used for the visualization of CTLA-4 in a melanoma mouse model." (PMID 33353213, 2020). "Notably, TERT mutant patients may benefit from anti‐CTLA4 treatment, especially for melanoma." (PMID 32810393, 2020). "But, case reports on abscopal effects occurring with the combination of anti-CTLA4 and SRT in patients with melanoma are increasing and suggest a clinical benefit in terms of survival." (PMID 33050910, 2020). "Ipilimumab, an inhibitor of CTLA-4 (anti-CTLA-4), has been approved for the treatment of advanced or unresectable melanoma This agent has been shown to be effective as monotherapy and in combination with nivolumab (anti-PD-1)." (PMID 32013263, 2020). "Currently, seven antibodies targeting three major immune check point proteins (anti-CTLA4, anit-PD1 and anti-PDL1) have been approved by the FDA for the treatment of several different tumor entities, including KRASmut melanoma and non-small cell lung cancer." (PMID 32796566, 2020). "In melanoma models, tumors undergoing EMT lack E-cadherin expression and thus are resistant to anti-PD-1 and anti-CTLA-4 therapies." (PMID 32380703, 2020). "When Imatinib within tLyp1 peptide-conjugated nanoparticles was combined with anti-CTLA-4 antibody, the authors found an enhanced downregulation of suppressive Tregs and activation of CD8+ effector T cells in the B16/B6 melanoma model." (PMID 32942725, 2020). "This is the first report to establish the association between the overexpression of immunoproteasome subunits PSMB8 and PSMB9 and improved survival and enhanced response to immune-checkpoint inhibitors (both anti-CTLA4 and anti-PD1) in melanoma patients." (PMID 32060274, 2020). "Recently therapy that targets the MAPK signaling (BRAF/MEK inhibitors) and immunotherapy (anti-CTLA4 and anti-PD1 agents) have changed the therapeutic approaches to stage IV melanoma." (PMID 32575838, 2020). "The current therapies for advanced stage disease in melanoma are based on the inhibition of either the aberrantly activated BRAF/MEK pathway, or the immune checkpoints PD1 and CTLA4." (PMID 33193402, 2020). "PLS-DA resulted in a CCR of 100% and 93% in the anti-CTLA-4 and anti-PD1 melanoma discovery cohorts, respectively." (PMID 33427690, 2020). "Antibodies against the first discovered ICI, CTLA-4, PD-1 and PD-L1, have shown significant activity in phase III studies against melanoma and other solid cancers, alone or in combination with chemotherapy or radiotherapy." (PMID 32443877, 2020). "Overexpression of IKZF1 in melanomas enhanced the recruitment of immune infiltration and sensitivity to PD1 and CTLA4 inhibitors." (PMID 32850314, 2020).
melanoma (continued). "Concerning the type of neoplasia, the vast majority of studies regard patients with melanoma or NSCLC, treated with anti-CTLA-4 or anti-PD-1 or, in few cases, with both of them." (PMID 32265933, 2020). "The anti-CTLA-4 antibody Ipilimumab, in combination with the anti-PD-1 antibody Nivolumab, has been FDA-approved for the treatment of melanoma, lung cancer, and renal cell carcinoma, among other cancers." (PMID 33256070, 2020). "The combination of anti-CTLA-4 monoclonal antibodies, anti-PD-L1 monoclonal antibodies, and the IDO inhibitor INCB23843 in the murine B16.SIY melanoma model showed markedly improved tumor control over single-drug treatment." (PMID 31911758, 2020). "Since 2011 the prognosis of systemic melanoma has profoundly changed with the introduction of new targeted therapies, as BRAF inhibitors and MEK inhibitors and immunotherapy (anti-CTLA-4 and anti-PD-1)." (PMID 32575838, 2020). "We are therefore cautious in making further derivations of the study group into smaller subgroups (e.g. separate analysis of scalp melanoma and other head and neck skin regions, or separate comparison of the effect of PD1 versus CTLA4 inhibitors)." (PMID 32282861, 2020). "Four patients received combination anti-CTLA4 and anti-PD1, including two patients with melanoma, one with breast cancer and one patient with renal cell carcinoma." (PMID 32983574, 2020). "CTLA-4-NF (NCT03110107) and CTLA-4-Probody (NCT03369223) are two ipilimumab-based compounds that are being tested in patients with solid tumors, including melanoma." (PMID 32503946, 2020). "In 75 melanoma patients with a total of 566 brain metastases, given a median of 20 Gy SRS and anti‐PD‐1/anti‐CTLA‐4, concurrent immunotherapy and SRS led to a greater median per cent reduction in lesion volume than non‐concurrent therapy." (PMID 32994997, 2020). "The simultaneous inhibition of PD1 and CTLA4 or TIM3 in advanced melanoma patients show promise in clinical trials." (PMID 32728493, 2020). "Therefore, TERT mutant patients may benefit from anti‐CTLA4 treatment, especially for melanoma." (PMID 32810393, 2020). "Responses to inhibition of CTLA-4 by ipilimumab in mouse models of MCA205 sarcoma, RET melanoma, and MC38 colon carcinoma were inferior in germ-free or in broad-spectrum antibiotic treated mice." (PMID 32817793, 2020). "Initial interest in TMB was triggered by two exploratory studies of WES data obtained from patients with melanoma; a correlation between TMB and the magnitude of clinical benefit in ipilimumab (anti-CTLA-4)-treated patients was observed." (PMID 33268350, 2020). "Synergistic retardation of tumor outgrowth by anti-CTLA-4, anti-PD-L1 and/or IDO inhibition (INCB23843) was confirmed in a murine B16.SIY melanoma model." (PMID 33072086, 2020). "When compared to standard treatment with chemotherapy, an increase in overall survival was noted with the use of anti-CTLA-4, especially in patients diagnosed with RCC, melanoma and NSCLC." (PMID 32867025, 2020). "Anti-CTLA-4 IgG2 tremelimumab was the first ICI antibody to be tested and gave some promising results, especially in terms of duration of response in melanoma patients." (PMID 32443877, 2020). "For melanoma and NSCLC, TMB was correlated with clinical outcome after anti-CTLA-4 and anti-PD-1 immunotherapy, respectively." (PMID 32610601, 2020). "in combination an anti-CTLA-4 (9H10 clone, four doses of 5 mg/kg on alternate days) resulted in increased anti-tumor activity against B16F1 melanoma cells." (PMID 33212945, 2020). "In particular, combination of anti-PD-1 nivolumab and anti-CTLA-4 ipililumab has been tested in Phase II or III studies in a number of solid cancers, from melanoma, to renal, colon, esophageal, sarcoma, lung cancers and mesothelioma." (PMID 32443877, 2020).
melanoma (continued). "Currently, CTLA-4 inhibitors mainly include Tremelimumab and Ipilimumab, which have been successively approved by the FDA for the treatment of melanoma, non-small cell lung cancer, advanced kidney cancer and other tumors 9-11." (PMID 33033520, 2020). "CTLA-4 clinical trials led to FDA approval of ipilimumab and prompted further investigations on melanoma metastasis." (PMID 33167514, 2020). "In this study, a triple combination of immunotherapies was devised, and it included the anti-CTLA-4 monoclonal antibody, which was the first FDA-approved immune-checkpoint blocker for the treatment of melanoma." (PMID 32596146, 2020). "In melanoma patients treated with ICI, these neurological adverse events occur in 1% (anti-CTLA4), 3% (anti-PD1) or 14% (anti-CTLA4 and anti-PD1) of the population." (PMID 32856125, 2020). "Ipilimumab, the CTLA-4 inhibitor, has been approved by the FDA for the treatment of patients with advanced melanoma." (PMID 32992835, 2020). "The active immune class shares high similarity with melanoma patients who responded to treatment with MAGE-A3 (bottom left) and BALB/c mice who responded to treatment with anti-CTLA-4 (bottom right)." (PMID 31998649, 2019). "In this context, the combination of different checkpoint inhibitors (anti-CTLA-4 and anti-PD1 Abs) yielded better results in melanoma patients, but with increased toxicity." (PMID 30792754, 2019). "Furthermore, lack of response to anti-PD-1 or anti-CTLA-4 therapy in another melanoma cohort has been associated with baseline abundance in Ruminococcus obeum, which contradicts other preclinical/clinical data supporting that gut enrichment with Ruminococcaceae family and Ruminococcus spp." (PMID 30887236, 2019). "Ipilimumab, the first anti-CTLA-4 antibody was approved by the US Food and Drug Administration (FDA) in 2011 for melanoma." (PMID 30987642, 2019). "Monoclonal antibodies targeting immune-checkpoints (CTLA-4 and PD-1/PDL-1) have revolutionized the management of several advanced malignancies, particularly melanoma and NSCLC." (PMID 30886831, 2019). "Blocking immune checkpoints like CTLA-4 or PD-1 for unleashing antitumor immune responses are a promising strategy, as CTLA-4 blockade has led to increased survival in solid cancers like melanoma." (PMID 31628525, 2019). "This was demonstrated in the experiment where anti-PD-1 antibody alone or together with anti-CTLA-4 antibody were used in mice with set MCA-205 sarcoma and RET melanoma." (PMID 31003463, 2019). "B7 family members have recently drawn attention, especially following the success of anti-CTLA4 and anti-PD1/PDL1 therapy in advanced stage melanoma and other solid tumors." (PMID 31412888, 2019). "Ipilimumab, a fully human monoclonal antibody IgG1 that inhibits the interaction between CTLA-4 and its ligands, was approved by FDA in 2011 for the treatment of unresectable stage III/IV melanoma, owing to the improvements in clinical outcomes." (PMID 31134073, 2019). "Nivolumab, a programmed cell death protein 1 (PD-1) antibody, and ipilimumab, a cytotoxic T-lymphocyte antigen 4 (CTLA-4) antibody, are immune checkpoint inhibitors (ICI) which have emerged as first- and second-line therapy of stage IV melanoma." (PMID 30791949, 2019). "In vivo, Nrp-1+PD-1hi CD8+ tumour-infiltrating lymphocytes (TIL) in B16F10 melanoma are enriched for tumour-reactive T cells exhibiting an exhausted state, expressing Tim-3, LAG-3 and CTLA-4 inhibitory receptors." (PMID 31350404, 2019). "Recent reports have shown that combined inhibition of IDO and immune checkpoint inhibitors (CTLA-4, PD1, and PD-L1) synergize in melanoma mouse models." (PMID 30853982, 2019). "This knowledge led to the development of the current first-line therapies of inoperable, advanced stage melanomas targeting mediators of the ERK/MAPK pathway: RAF, MEK kinases, or the CTLA-4, PD-1/PDL-1 immune checkpoints using humanized monoclonal antibodies." (PMID 31426515, 2019).